PCSK9 (proprotein convertase subtilisin/kexin type 9)
Diseases named in the same sentence as PCSK9 in open-access papers (continued):
Sharing a sentence is not in itself a finding about the gene and the disease.
myocardial infarction (continued). "The level of plasma PCSK9 is positively correlated with hs-CRP in myocardial infarction patients." (PMID 36970356, 2023). "In this context, authors found that the addition of the lipids’ lowering agents (PCSK9 inhibitor) to high-intensity statin therapy in patients with acute myocardial infarction, reducing the blood lipids values significantly, resulted in favorable effects on coronary atherosclerosis." (PMID 37005586, 2023). "Both PCSK9 inhibitors (evolocumab and alirocumab), having received FDA approval in 2015, have been approved for use in people with existing CV disease to reduce the risk of stroke, myocardial infarction, and coronary revascularization." (PMID 37937036, 2023). "Kaplan–Meier survival curves compared conventional lipid-lowering therapy with and without 3 months of PCSK9 antibody administration for the composite of all-cause death, myocardial infarction, stroke, unstable angina, and ischemia-driven revascularization." (PMID 37233171, 2023). "It had been reported that hypoxia and myocardial infarction upregulates PCSK9 in cardiac tissues." (PMID 35742954, 2022). "We reported that early initiation of evolocumab, a proprotein convertase subtilisin/kexin type 9 inhibitor, in addition to a statin substantially reduced the lipoprotein(a) levels in patients with acute myocardial infarction (AMI) after primary percutaneous coronary intervention (PCI)." (PMID 35621864, 2022). "This study aimed to investigate whether the administration of the PCSK9 inhibitor evolocumab combined with statin therapy in patients with acute myocardial infarction can reduce the prevalence of CI-AKI better than statin therapy alone." (PMID 36051574, 2022). "However, our study is in line with clinical data showing that low PCSK9 activity is associated with low LDL-C and a lower risk of myocardial infarction." (PMID 35742954, 2022). "They found a significant association between myocardial infarction and lipid metabolism-related gene variants, such as lipoprotein lipase (LPL), apolipoprotein E (APOE) and proprotein convertase subtilisin/kexin type 9 (PCSK9), as well as eNOS gene variants." (PMID 34564134, 2021). "Thus, it is noteworthy to mention, that recent investigations have shown a relationship between serum PCSK9 levels and cardiovascular events as e.g. myocardial infarction, revascularization, thrombotic stroke." (PMID 32942987, 2020). "Experimental and clinical studies regarding the role of PCSK9 in myocardial infarction." (PMID 33262707, 2020). "Therefore, in this study we sought to investigate the effects of PCSK9 inhibitor administration in the rodent cardiac I/R model on myocardial infarct size, arrhythmias, left ventricular (LV) function and mitochondrial function and dynamics." (PMID 31557388, 2019). "In addition to alirocumab and evolocumab for cholesterol-lowering and evolocumab for the prevention of heart attack and stroke, which are the only two approved inhibitors of PCSK9, bococizumab is another monoclonal antibody against PCSK9." (PMID 31547243, 2019). "Moreover, findings from that study 15 had a limitation for its clinical application to acute myocardial infarction cases since PCSK9 inhibitor was given only prior to myocardial ischaemia." (PMID 31557388, 2019). "A limited number of studies have explored whether the role of circulating proprotein convertase subtilisin/kexin type 9 (PCSK9) in the pathogenesis of acute myocardial infarction (AMI) is sex specific." (PMID 30816133, 2019). "Recent randomized trials have shown comparable effects of PCSK9-inhibition on IS and myocardial infarction, although the lower confidence limits are also consistent with a weaker effect on IS than on myocardial infarction (8% vs. 18% risk reduction, respectively)." (PMID 29020353, 2018).
myocardial infarction (continued). "One of the meta-analyses studied myocardial infarction rates and showed a significantly lower rate (0.6 %; 19/3289 patients) in PCSK9 inhibitor-treated patients compared to those who received no anti-PCSK9 treatment (1.0 %; 19/1906 patients; odds ratio, 0.49; 95 % CI, 0.26–0.93)." (PMID 26456772, 2015). "Recent studies have shown that elevated levels of circulating PCSK9 are associated with increased platelet reactivity and thrombosis; however, the effect and mechanism of PCSK9 on cardiac repair after myocardial infarction through the induction of platelet activation remain unclear." (PMID 41573336, 2026). "Our previous studies revealed that PCSK9 affects cardiac function after MI (myocardial infarction) by promoting myocardial fibrosis." (PMID 41573336, 2026). "Taken together, myocardial infarction leads to a surge in PCSK9 concentrations in plasma, liver, and heart, suggesting a relevant role of PCSK9 in particular during the inflammatory phase of post MI cardiac remodeling." (PMID 39906341, 2024). "Indeed, one small, open-label, 1:1 randomised trial involving 36 participants reported that fc-PCSK9 levels were transiently upregulated following myocardial infarction (MI) and that these levels were significantly reduced with treatment of the PCKS9 inhibitor evolocumab." (PMID 39273186, 2024). "Increased PCSK9 concentrations also increased microvascular obstruction, and thus, they increased myocardial necrosis in myocardial infarction (MI)." (PMID 36768292, 2023). "By investigating the functional role of PCSK9 inhibitions in the metabolic targets, it could potentially lead to better understanding of the pathogenesis of myocardial infarction and ischemic stroke, as well as provide a potential therapeutic target for its management." (PMID 37860186, 2023). "Apart from its role in hepatic LDL clearance, the extrahepatic functions of PCSK9 have been described, and as such, an increase in platelet activity via PCSK9 might contribute to an increased incidence and progression of acute myocardial infarction (AMI)." (PMID 35742954, 2022). "Moreover, this study only investigated the incidence of CI-AKI in patients with acute myocardial infarction; the effect of PCSK9 inhibitors on CI-AKI incidence in other ASCVD (Atherosclerotic Cardiovascular Disease) patients undergoing PCI remains to be prospectively studied." (PMID 36051574, 2022). "The GS odds ratio (OR) for myocardial infarction (MI) was 0.53 (95% CI 0.42; 0.68), compared to a PCSK9 inhibitor effect of 0.90 (95% CI 0.86; 0.93)." (PMID 31664920, 2019). "Mutations that block PCSK9 secretion reduce LDL-cholesterol and the incidence of myocardial infarction (MI)." (PMID 25180781, 2014). "For example, a variant in the PCSK9 gene has been associated with a substantial decrease in serum LDL-C levels and almost abolished myocardial infarction (MI) risk." (PMID 18714375, 2008). "PCSK9 promotes platelet activation, induces the secretion of platelet‐derived TGF‐β, and thereby accelerates myocardial fibrosis after myocardial infarction." (PMID 41573336, 2026). "Clinical myocardial samples have demonstrated pronounced co-localisation of PCSK9 with N-terminal gasdermin D (GSDMD-NT) in the peri-infarct zone, implicating PCSK9 in pyroptotic injury during acute myocardial infarction." (PMID 41008547, 2025). "The FurtherCardiovascular Outcomes Research With PCSK9 monoclonal antibody (FOURIER) trialinvestigated patients with stable atherosclerotic cardiovascular disease and aprevious myocardial infarction (MI)." (PMID 39076939, 2024). "In both animals and humans, there is a significant concomitant increase in the expression of PCSK9, NLRP3, caspase-1, IL-1β, and IL-18 in both chronic myocardial ischaemia and acute myocardial infarction." (PMID 38886277, 2024). "Despite its known effects on cholesterol metabolism, the role of PCSK9 in cardiac function, especially post-myocardial infarction (MI), remains unclear." (PMID 39906341, 2024).
myocardial infarction (continued). "For example, inhibition of PCSK9 was demonstrated to reduced myocardial ischemia-/reperfusion injury via BNIP-3 mediated autophagic pathway and improved myocardial infarct size and subsequent cardiac function." (PMID 37860186, 2023). "PCSK9 inhibitors can further reduce plasma LDL-C in addition to statins treatment at the maximum dose, which is beneficial to the prognosis of myocardial infarction." (PMID 36970356, 2023). "Atherogenic lipoproteins are significantly reduced by proprotein convertase subtilisin/kexin type 9 inhibitors (PCSK9-i), leading to a lower incidence of myocardial infarction and stroke." (PMID 37898751, 2023). "These figures suggested that inhibition of highly expressed PCSK9 after AMI reduced the infarct size, myocardial fibrosis, and inflammatory response and promoted cardiac function repair after acute myocardial infarction." (PMID 35832650, 2022). "The use of PCSK9 inhibitors, hydration therapy, and statin administration appears promising for preventing CI-AKI in patients with acute myocardial infarction undergoing PCI." (PMID 36051574, 2022). "Evolocumab and alirocumab are novel developed proprotein convertase subtilisin/kexin type 9 (PCSK9) inhibitors that have been shown to be effective and safe in patients with stable angina and previous myocardial infarction." (PMID 36632288, 2022). "Moreover, a study using an acute myocardial infarction (AMI) rat model was the first to show a relationship between MI and PCSK9." (PMID 36005422, 2022). "PCSK9 plays a key role in raising LDL-C levels, which contributes to heart attacks (MI)." (PMID 40357205, 2025). "Therefore, PCSK9 inhibitors can decrease LDL-C as well as thrombosis markers in patients with FH, preventing arterial clotting events, including heart attacks and ischemic strokes." (PMID 40732982, 2025). "Specifically, non-fatal myocardial infarction occurred in three (3%) vs. seven (7%), stroke in two (2%) vs. five (5%), and cardiovascular death in two (2%) vs. four (4%) in the PCSK9 and control groups, respectively." (PMID 40688979, 2025). "This study assessed the efficacy of PCSK9 inhibitors in reducing MACE, nonfatal myocardial infarction, stroke, cardiovascular death, and all-cause mortality in statin-intolerant patients." (PMID 40110272, 2025). "Among the individual components, non-fatal myocardial infarction occurred in three (3%) vs. seven (7%), stroke in two (2%) vs. five (5%), and cardiovascular death in two (2%) vs. four (4%) in the PCSK9 and control groups, respectively." (PMID 40688979, 2025). "Previous studies reported improved ejection fractions in PCSK9-KO mice following myocardial infarction but did not report any mortality." (PMID 39906341, 2024). "PCSK9 inhibitors lower LDL cholesterol and decrease incidence of strokes and myocardial infarction." (PMID 35275946, 2022). "Previous studies have shown that PCSK9 enhances thrombosis after acute myocardial infarction (AMI) by binding to platelet CD36, leading to increased MI size." (PMID 41573336, 2026). "An analysis from the OttawaHeart Genomics (OHGS) registry involving 45 individuals with acute myocardialinfarction (AMI) revealed significantly elevated PCSK9 levels before initiatingstatin compared to 398 coronary artery disease (CAD) cases without myocardial infarction (MI)." (PMID 39484117, 2024).
myocardial infarction (continued). "In pre-PCI statin and hydration therapy, the results showed that the prevalence of CI-AKI in patients with acute myocardial infarction who received evolocumab was 6.7%, which was significantly less than the rate of 20.0% in the group that did not receive the PCSK9 inhibitor." (PMID 36051574, 2022). "In the SPIRE outcomes trials of PCSK9-inhibitor therapy which were prematurely terminated (and so involved smaller numbers of events), the rate of non-fatal stroke was also reduced by at least as much as for non-fatal myocardial infarction." (PMID 29020353, 2018). "Two antibody‐based PCSK9 inhibitors have been successfully developed for clinical use, proving effective in lowering cholesterol levels and reducing the risk of ASCVD events, including myocardial infarction, stroke, and death, without significant adverse effects." (PMID 41509664, 2026). "Additionally, other observational studies have independently established a link between circulating PCSK9 levels and a diminished left ventricular ejection fraction (LVEF) following myocardial infarction (MI)." (PMID 38383373, 2024). "Here, we design a human PCSK9 mimic, named HIT01, with no consecutive 9-residue stretch in common with any human protein as a potential heart attack vaccine." (PMID 38819987, 2024). "The absence of a correlation between baseline PCSK9 and baseline LVEF indicates that PCSK9 was a predictor of future deterioration of LVEF over the months after the event, and that this effect was not due to a correlation that existed between PCSK9 and LVEF prior to the myocardial infarction." (PMID 35864531, 2022). "Recently, PCSK9 inhibitors have been shown to be effective in lowering LDL-C in patients with SI and to robustly reduce cardiovascular events in a broad spectrum of CAD patients with and without prior myocardial infarction." (PMID 31307391, 2019). "Lp(a) primarily binds to mature PCSK9 rather than furin-cleaved PCSK9, and evolocumab increases the mature form of PCSK-9 while halting the increase in plasma Lp(a) after acute myocardial infarction (MI)." (PMID 37686428, 2023). "PCSK9 inhibitors are now one of the emerging non-statin lipid lowering agents which exhibited an increasing clinical benefits in patients and are used in different cardiovascular diseases (CVD) especially coronary heart diseases (CHD), myocardial infarction (MI), and stroke." (PMID 36781714, 2023).
Stroke (108 papers, 2007 to 2026). Sudden impairment of blood flow to a part of the brain due to occlusion or rupture of an artery to the brain. "For example, the addition of evolocumab to statin therapy resulted in a decreased risk of ischemic stroke in patients with previous strokes who were treated with PCSK9 inhibitors." (PMID 40354375, 2025). "PCSK9-mAb significantly reduced the risk of stroke (RR 0.75; 95% CI 0.66–0.86, p < 0.0001) and MI (RR 0.81; 95% CI 0.76–0.87, p < 0.00001), but not the risk of cardiovascular death (RR 0.96; 95% CI 0.86–1.07, p = 0.45) compared with placebo." (PMID 38907775, 2025). "In conclusion, the investigation into the efficacy of pharmacologic agents targeting PCSK9 suggests an effect rather for lowering the risk of MI and stroke than for cardiovascular mortality." (PMID 38907775, 2025). "Cholesterol-lowing therapies using statins or proprotein convertase subtilisin/kexin 9 (PCSK9) inhibitors have been confirmed to mitigate stroke risk proportionally with the degree of reduction in cholesterol levels." (PMID 38166986, 2024). "In cerebrovascular disease, single nucleotide polymorphisms (SNPs) in the PCSK9 gene are associated with stroke risk." (PMID 38886277, 2024). "Some PCSK9 SNPs, such as rs505151, positively correlate with both a higher risk of stroke and severe CAD in the Tunisian population." (PMID 38886277, 2024). "When aggressive LDL targets (< 55 mg/dL) for high-risk patients with history of TIA or stroke cannot be attained with statin therapy alone, the addition of ezetimibe and/or PCSK9 (proprotein convertase subtilisin/kexin type 9) inhibitors is recommended." (PMID 39523357, 2024). "The aim of this review is to expound on the mechanism by which PCSK9 increases the risk of ischemic stroke as well as the efficacy and safety of PCSK9 inhibitors in the treatment of stroke." (PMID 38273837, 2023). "Encouragingly, the trial also found that Evolocumab inhibited the enhancement of platelet activity by PCSK9, indicating that patients at risk of stroke due to overactive platelets now have a new treatment option." (PMID 38273837, 2023). "Following statins, PCSK9 inhibitors were scored best for MI and stroke but second best for all-cause mortality and CV." (PMID 37937036, 2023). "Evolocumab is a PCSK9 inhibitor antibody approved to reduce the risk of MI, stroke, and coronary revascularization in adults with established CVD." (PMID 33760276, 2021). "Longitudinal studies investigating the value of circulating PCSK9 for predicting major adverse cardiovascular events (MACEs) or stroke or all-cause mortally with risk estimates and 95% confidence intervals (CI) were included in the analyses." (PMID 33738300, 2021). "The prespecified analyses designed to assess the effect of PCSK9 inhibitors on stroke demonstrated a reduction in risk of ischemic stroke (IS) without increasing hemorrhagic stroke, irrespective of baseline LDL-C and of prior IS history." (PMID 33738300, 2021). "Genetic evidence from the Hypertension Genetic Epidemiology Network (HyperGEN) and the Reasons for Geographic And Racial Differences in Stroke study (REGARDS) studies have shown that PCSK9 variation associated with blood pressure in African Americans." (PMID 34041285, 2021). "It has been well-elucidated that PCSK9 antibodies significantly decrease the risk of stroke in randomized trials of therapeutic PCSK9-inhibition as comparable to the effect on MACEs." (PMID 33738300, 2021). "REasons for Geographic and Racial Differences in Stroke (REGARDS) was a prospective cohort study of the association between PCSK9 loss-of-function variants (C697X or Y142X) and neurocognitive impairment and decline in 10,695 black individuals over 5.6 years." (PMID 32595449, 2020). "The main observation of this study was that the E670G SNP of PCSK9 gene associated significantly with LVA stroke risk in the Belgian population." (PMID 17940607, 2007).